LOHAN2 (lncRNA oncogene in head and neck cancer 2)
Synonyms: LINC01568
Gene: Long non-coding RNA gene on chromosome 16 (73,386,771 to 73,504,954, forward strand). Ensembl gene ENSG00000258779.
Diseases named in the same sentence as LOHAN2 in open-access papers:
LOHAN2 is named in the same sentence as 1 disease in open-access papers, as found by Europe PMC text mining. Sharing a sentence is not in itself a finding about the gene and the disease.
LOHAN2 shares sentences with these, for which no sentence is quoted: head and neck cancer (1 paper).